FOXP3 (forkhead box P3)
Diseases named in the same sentence as FOXP3 in open-access papers (continued):
Sharing a sentence is not in itself a finding about the gene and the disease.
tumor (continued). "As the tumor-infiltrating CD4+ cell population was elevated in oligo-synchronous BM, we further investigated the frequency of regulatory T cells (Tregs) defined by FoxP3 expression." (PMID 40346687, 2025). "Baseline tumor CD8+ count did not demonstrate any association with PFS, but co-clustering of CD8+ T cells with FOXP3+ Tregs was associated with poor disease outcome." (PMID 41282765, 2025). "Furthermore, LSD1 inhibition induced a comprehensive reshaping of the TME in xenografts, characterized by the upregulation of PD‐L1 expression in tumour cells, increased infiltration of CD8+ CTLs and decreased infiltration of FoxP3+ Treg cells." (PMID 40356247, 2025). "In this regard, we may speculate that the moderate increase in Foxp3 and PD-1 expression in colon tissue of CNF1 + DSS-treated mice may be an early consequence of the immune-suppressive and tumor-promoting modulation exerted by IL-10 and neutrophils." (PMID 39876002, 2025). "Studies have shown that a higher CD8+/FoxP3+ ratio in the metastatic core, rather than at the tumor–parenchyma interface, serves as an independent prognostic factor for postoperative survival." (PMID 40027151, 2025). "In most cancer types, PTEN loss was associated with a higher abundance of CD4+ lymphocytes, M1 macrophages, and FoxP3+ T regulatory cells, along with increased expression of immune checkpoints such as LAG3 and IDO1, indicating an immunosuppressive tumor microenvironment." (PMID 40650023, 2025). "The number of Foxp3+ cells in the control group determined by IHC was slightly higher than that of CD4+cells, likely due to the heterogeneous distribution of Foxp3+ cells within the tumor tissue." (PMID 40343532, 2025). "To evaluate the potential impact of TGF-β signaling on the tumor immune status, we correlated the tumoral pSMAD2 groups with tumor-infiltrating lymphocytes (TILs), the lymphocyte markers CD8 and FOXP3, as well as the immune checkpoint markers PD1 and PDL1 using categorized variables." (PMID 40488800, 2025). "Immune escape by forkhead box protein P3 (FOXP3+) immunoregulatory T cells and the programmed death-ligand 1 (PD1/PD-L1) axis, mechanisms best described in the context of invasive neoplasms, may play a role in the evolution of pre-malignant lesions." (PMID 40270290, 2025). "Indeed, initiation of GC shutdown has previously been shown to involve both TFH cells expressing FoxP3, PD-1 and BCL6 and ICOS-expressing Tregs that inhibit anti-tumor reactions." (PMID 40211433, 2025). "The density of PD-1+FOXP3+CD4+ cells and PD-L1–expressing cells was higher in group 1 than in group 2, suggesting that immunosuppressive Tregs and PD-L1 expression by the tumor may impede long-term responses to T-DXd." (PMID 39679910, 2025). "Consequently, the CD8a/FoxP3 ratio was elevated in Axl KO tumors, although this was only statistically significant in MOC2-398, indicating a shift towards a more anti-tumor immune profile." (PMID 40149328, 2025). "Next, CD3+CD8+ T cell, CD4+FOXP3+ TReg, PDL1Tumor, NOS2Tumor, COX2Tumor, IDO1, and B7H4 density heatmaps were spatially examined relative to stroma as well as viable and necrotic annotated tumor regions." (PMID 40663402, 2025). "Within the TC-TLS, there was a greater abundance of various T cell subsets, including CD8+PD-1+, CD8+PD-1+TIM-3−, CD8+LAG-3−PD-1+TIM-3−, CD8+TIM-3-, CD8+LAG-3−TIM-3−, CD4+FoxP3−, CD4+CTLA-4−, and CD4+PD-L1+ T cells, compared with that in the tumour and stromal regions." (PMID 39901202, 2025). "Notably, an increase of cytotoxic CD8 + T-lymphocytes, decrease of regulatory FOXP3 + lymphocytes and increased function of natural killer cells in tumors has been described, supporting the hypothesis that metformin may favorably alter the tumor microenvironment." (PMID 40468055, 2025). "However, the CD8+, FOXP3+, and IBA1+ cell/tumor cell ratio increased from the core to the transition zone, and the CD8+ and IBA1+ cell/tumor cell ratio increased again to the periphery." (PMID 40996683, 2025).
tumor (continued). "FoxP3+ Tregs establish a robust immunosuppressive network by overexpressing checkpoint molecules (CTLA-4, PD-1, LAG-3) and secreting inhibitory cytokines (IL-10, TGF-β, IL-35), thereby creating an immune-privileged niche for tumor survival." (PMID 40563359, 2025). "Furthermore, the proportion of CD4+CD25+FoxP3+ Tregs in tumors decreased by approximately 10% in the poly IC + IF4G3986–994 group, indicating a reduction in the immunosuppressive tumor microenvironment alongside robust immune activation." (PMID 40283929, 2025). "Importantly, the net immune contexture in tumors—CD8+ infiltration, FOXP3 reduction, M1-type macrophage increasing, and IFN-γ–responsive protein enrichment—also indicates a Th1/Th17-dominant state that coincides with tumor control." (PMID 41455906, 2025). "Notably, our study revealed a significant correlation between tumor markers (β-HCG and AFP) and the proportion of infiltrating CD4+ and Foxp3+ cells, as well as CTLA-4 expression." (PMID 39958339, 2025). "The number of Tregs (FOXP3+, CD25high) and the expression of CTLA-4/CD39 correlate with immunosuppression and diminished responsiveness to immune checkpoint inhibitors across various tumor types." (PMID 41465319, 2025). "Consistent with this, IHC and immunofluorescence (IF) assays on tumor tissue samples obtained from HCC patients also demonstrated reduced CD8+ T cell infiltration and increased Foxp3+ Treg infiltration in HCC samples with high Gal1 expression compared to those with low Gal1 expression." (PMID 39853961, 2025). "Metformin may also favorably alter the metabolic and immunological tumor microenvironment in HNSCC patients, by reducing hypoxia and increasing the CD8/FOXP3 ratio, respectively." (PMID 40468055, 2025). "Conversely, patients with low Foxp3+ Treg infiltration had worse OS, PFS and RFS, indicating that Foxp3+ cells may play a critical role in anti-tumor immunity and are important for controlling CNS GCT progression." (PMID 39958339, 2025). "Similarly to the subcutaneous transplantation model, the tumor specimens generated from the KO cells showed upregulated LDHA expression, decreased CD8+ T cell infiltration, and increased Foxp-3+ Treg cell infiltration." (PMID 40139191, 2025). "On the other hand, Tregs are FOXP3- and CD25-positive CD4+ T lymphocytes (CD4+CD25+FoxP3+) that promote immunosuppression and a tolerogenic tumor microenvironment by secreting inhibitory cytokines such as TGF-β and IL-10 and by interacting with other immune cells." (PMID 40805183, 2025). "Mechanistic studies on Foxp3+ Treg-mediated protumor effects reveal their suppression of CD8+ CTL cytotoxicity and enhancement of tumor invasiveness, with elevated Foxp3+/CD8+ and Foxp3+/CD4+ ratios confirmed as independent risk factors for postoperative recurrence." (PMID 40510347, 2025). "However, Tregs, characterized by FOXP3 and CD25 expression, suppress anti-tumor responses through both cytokine-dependent (e.g., IL-10, TGF-β, IL-35) and contact-mediated mechanisms, dampening the activity of effector T cells, dendritic cells, and NK cells." (PMID 40660400, 2025). "Indeed, many studies have confirmed the poor prognostic role of the tumor-infiltrating PDL-1, CTLA-4, PD-1, and FOXP3 immunological markers in BC tissue, however, the role of the circulating levels of these markers is still a debatable issue." (PMID 40108523, 2025). "CGB5-expressing tumor cells convert conventional CD4+ T cells into Tregs by up-regulating the immunosuppressive cytokines TGF-β and IL-10, together with the transcription factor FOXP3." (PMID 41048937, 2025). "The galectin-3 produced by tumor cells and macrophages blocks CD8+ T cell activation signals and induces T cell apoptosis by interacting with LAG3 on the T cell surface; while FOXP3+ Tregs suppress anti-tumor immunity by secreting various inhibitory cytokines, such as TGF-β, IL-10 and IFN-γ." (PMID 41219968, 2025).
tumor (continued). "Published data suggest that MSCs, tumor cells, and their respective extracellular MVs possess immunosuppressive activity that inhibits cytodestructive immune responses, at least in part, through the enhancement of regulatory CD4+CD25+FoxP3+ T cell function." (PMID 41155635, 2025). "Conversely, the increased FOXP3+ Tregs and the decreased CD4+ and CD8+ T cells indicate an immunosuppressive microenvironment mediated by SjE16.7, which may facilitate tumor progression." (PMID 41011849, 2025). "We analyzed the relationship between tumor‐infiltrating immune cells (CD4, CD8, FOXP3, CD163‐positive cells) and proteins (TGFβ1 and its downstream signal, SMAD3) expression and survival after the start of combined therapy with immune checkpoint inhibitors plus chemotherapy in SCLC." (PMID 41187938, 2025). "For patients with present CD8+FoxP3+PD-1+ cells, we divided them into two groups based on the presence or absence of tumor cells within 30 μm: proximity-high and -low." (PMID 40422521, 2025). "Due to the lack of association between change in FOXP3 expression and AZD8701 dose or tumor shrinkage, it is not possible to draw any definitive conclusions about the significance of the observed changes." (PMID 39937271, 2025). "The higher expression of FOXP3 and CD163, specifically in the hematologic metastasis, suggests a more immunosuppressive tumor microenvironment at this stage of the disease, possibly reflecting greater infiltration of Tregs and M2-type macrophages, respectively." (PMID 41179298, 2025). "Moreover, tumor-infiltrating MAIT cells in CRC are CD4+ and Foxp3+ and express high levels of CD39, which is an exhaustion indicator." (PMID 40422223, 2025). "Studies have analyzed tumor tissues from mouse models of B-cell lymphomas and human cases of condylomatous and follicular lymphomas, revealing high expression of OX40 and CTLA-4 on the surface of tumor-specific Tregs (CD4+, Foxp3+)." (PMID 40356928, 2025). "Oppositely, the p38 blockade did not affect the proportion of tumor infiltrating regulatory T cell (Treg) populations expressing CD4+CD25+Foxp3+ markers, suggesting that the observed effects on CD8+ T cell exhaustion are not related to Treg populations." (PMID 41282257, 2025). "The observed phenomenon of a non-linear relationship of FOXP3 mRNA expression across tumor stages in both our experimental and TCGA validation cohorts warrants further investigation." (PMID 40806346, 2025). "CD8+–FOXP3+ cell clustering significantly influenced progression-free survival, independent of CD8+ T-cell density, underscoring the relevance of spatial immune colocalization within the tumor microenvironment." (PMID 41282765, 2025). "The expression levels of ALG3 in tumor cells and stromal cells were positively correlated with the abundance of CD4+ FOXP3+ regulatory T cells (Tregs), CD3+CD4+ T cells and PD-L1, whereas they were negatively correlated with the abundance of CD8+ T cells and CD68+CD86+ macrophages." (PMID 40475760, 2025). "This inflammation-dependent requirement for continuous Foxp3 activity enabled induction of a selective anti-tumor immune response upon systemic Foxp3 depletion, without causing deleterious T cell expansion in healthy organs." (PMID 40478934, 2025). "Notably, regarding Fib_CD74+–CD4T_FOXP3+ MHC-I ligands (HLA-A/B/C) only exist in normal samples, while in the tumor microenvironment, Fib_CD74+ promotes the recruitment of CD4T_FOXP3+ through the binding of CCL5 to the CCR4 receptor." (PMID 40948762, 2025). "VSIG4-positive macrophages in the tumor microenvironment may promote cancer progression and correlate with low CD8+ T-cell frequency, high Foxp3+/CD8+ infiltrating T-cell ratios, and poor prognosis." (PMID 41376629, 2025).
tumor (continued). "When mammary tumors were pretreated with image-guided fractionated radiation therapy (IGRT) followed by anti-TAG72-IL-2 therapy, an improved tumor growth inhibition was observed along with an increased tumor infiltration of IFNγ+ CD8+ T cells and a significant reduction in Foxp3+ CD4+ cells." (PMID 40361381, 2025). "In the group receiving 12.5 mg/kg of MP4, Treg populations (CD4+FoxP3+) were reduced by 50% in tumor samples, but not in blood and spleen, indicating a more specific targeting of Tregs in the TME contributing to the anti-tumor immune response." (PMID 40034859, 2025). "Tumor tissues in the CPPM+ group had the lowest percentage of CD3+ CD4+ Foxp3+ T cells, and the ratios of CD3+ CD8+ T cells and CD3+ CD4+ T cells to CD3+ CD4+ Foxp3+ T cells were up to 5-fold in the CPPM+ group." (PMID 40491506, 2025). "Tumor-infiltrating lymphocytes (TILs) were evaluated via hematoxylin and eosin stains, and immunohistochemistry was used to assess programmed death-1 (PD-1), PD-L1, cluster of differentiation 8 (CD8), and forkhead box P3 (FOXP3) expression." (PMID 40035906, 2025). "Notably, the proportion of Foxp3+CD4+ Tregs was markedly decreased in the Se@MI-treated group, further supporting the notion that Se@MI reshapes the tumor immune microenvironment by mitigating immune suppression." (PMID 41246348, 2025). "A previous study showed that Treg cells from both the tumor microenvironment and dLNs in HNSCC patients exhibited a CCR6+ effector Treg cell phenotype, and CCR6+ Treg cells expressed a higher level of FOXP3 than CCR6− Treg cells, which indicated a stronger suppressive function." (PMID 40290124, 2025). "(J) Multiplexed IF staining showing that the recruitment of FOXP3 + cells toward SLC26A3high cells might induce EMT (marked with E-cadherin) and increase the stemness (marked with ALDH1A1) of tumor cells, via TGF-β pathway." (PMID 40066698, 2025). "Minimal changes in percentages of FoxP3+ Tregs were observed, indicating that modakafusp alfa does not enhance a Treg-mediated suppressive tumor microenvironment." (PMID 41445795, 2025). "FOXP3 was highlighted as a critical gene influencing ICD, where its knockdown significantly reduced ccRCC cell proliferation and migration, underscoring its role in tumor progression." (PMID 39883234, 2025). "Furthermore, recombinant human CCL11 has been shown to expand the CD4+CD25+Foxp3+ regulatory T-cell (Treg) population while upregulating both CCR3 and Foxp3 expression in tumor microenvironments." (PMID 40429807, 2025). "Spearman correlation analysis of FOXP3 mRNA expression across tumor stages revealed a significant negative correlation between tumor stage and FOXP3 expression in both cohorts, with expression gradually decreasing toward advanced stages." (PMID 40806346, 2025). "Furthermore, the regressing tumor exhibited a rise in both CD163:CD68 and FoxP3:CD4 ratios, suggesting that the inflammation driving STR was associated with an upregulation in immunosuppressive M2 macrophages and regulatory T-cells (Tregs), respectively." (PMID 40594889, 2025). "One of the most intriguing findings of this study is the non-linear trajectory of FOXP3 expression across tumor stages, validated in both the MMA and TCGA cohorts." (PMID 40806346, 2025). "Therefore, we conclude that PD-1/Al@OV facilitates macrophage clearance and enhances T cell (CD3+ cells) infiltration in tumor tissue, particularly increasing cytotoxic T cell (CD8+ cells) infiltration while reducing Treg cells (FOXP3+ cells)." (PMID 39955603, 2025). "Furthermore, in the tumor parenchyma, both the proportion and the cell density of YAP1-positive cells are positively correlated with that of FOXP3-positive cells." (PMID 40051494, 2025). "The proliferation, Foxp3 gene expression, and FOXP3 protein expression of tumor-infiltrating Treg cells was not significantly different between groups, which was also true for most traditional surface markers of Treg cell suppressive function." (PMID 40100289, 2025).
tumor (continued). "Although LMO7 did not promote an increase in the percentages of CD3+ T cells, CD3+ CD8+ T cells, CD163+ macrophages, GranzymeB+ cells, and CD3+ FOXP3+ T cells among all nucleated cells, it induced Treg and dysfunctional CD8+ T cells to be in closer proximity to tumor cells." (PMID 39143228, 2025). "In the same analysis, when analyzing the effect of tumor infiltration with “regulatory” T cells [expressed as FOXP3(+) T cells], a negative effect on overall survival was noted." (PMID 40563621, 2025). "Unexpectedly, we detected greater fractions of FoxP3+ Treg cells in both the tumor core of responding animals and the tumor periphery of nonresponsive animals." (PMID 40561008, 2025). "In contrast, Foxp3 protein depletion caused a preferential expansion of effector CD4 and CD8 T cells in the tumor-draining, but not the non-draining lymph node." (PMID 40478934, 2025). "The tumor-derived exosomes from the KRAS-mutant NSCLC patients have been found to transform naïve CD4+CD25−T cells to CD4+FoxP3+ Treg-like cells, a process independent of cytokine signaling." (PMID 41184283, 2025). "In the tumor microenvironment, IDO is commonly expressed by myeloid cells and suppresses CD8+T cell activity through multiple mechanisms, including the induction of FOXP3+ regulatory T cells and the inhibition of CD8+T cell function." (PMID 40232951, 2025). "In summary, the presence of CD8+FoxP3+PD-1+ cells in advanced NSCLC tissues and their close spatial proximity to tumor cells might be crucial for favorable survival outcomes in patients receiving immunotherapy." (PMID 40422521, 2025). "To confirm the localized effect of Foxp3 protein depletion, we next compared the tumor-draining and non-draining lymph nodes of mice within the same treatment groups." (PMID 40478934, 2025). "Additionally, forkhead box P3 (FOXP3)-targeting peptides reduce Treg activity, reversing the immunosuppressive environment that allows tumor cells to evade immune detection." (PMID 40612874, 2025). "Indeed, the inhibition of EZH2 decreases FOXP3 expression on Treg cells, mitigating their immunosuppressive activity and promoting the recruitment of CD8+ T cells within the tumor microenvironment." (PMID 40554927, 2025). "Nevertheless, for a better understanding of the interaction of chlorambucil’s effect on the tumor microenvironment, it would be necessary to include markers for PD-L1, Treg lymphocytes (FOXP3), and CD8 T lymphocytes, which was not performed." (PMID 39239387, 2024). "The FOXP3 overexpression was confirmed in NSCLC cells and also tumor-infiltrating lymphocytes." (PMID 38674427, 2024). "In RIC-treated tumors, the number of CD3 (p=0.006), but not FoxP3- positive cells (p = 0.84), in the tumor core was significantly higher compared to the control group." (PMID 39650654, 2024). "Furthermore, tumor‐infiltrated T cells (CD3+ and CD8+) and CD11c+ macrophages were significantly increased in the response group, while CD163+ macrophages and FOXP3+ Treg cells were decreased after NACT." (PMID 38778559, 2024). "Intriguingly, the majority of CD3+FOXP3+ T-cells accumulated near perivascular regions rather than in the tumor core or at the tumor edge, appearing trapped." (PMID 39123357, 2024). "The current findings indicate that CD25+FOXP3+CD45RA− effector Treg cells may be a useful prognostic biomarker and a potential target for manipulating tumor chemosensitivity to improve patient prognosis." (PMID 39232704, 2024). "Hypocellularity was observed in all major T cell subpopulations, with an absolute cell count normalized to the control of 56.78 ± 12.67%, 55.17 ± 12.59% and 70.68 ± 15.95% for CD8+, helper (CD4+ FOXP3−) and regulatory (CD4+ FOXP3+) T cells, respectively, on day 4 after tumor IR." (PMID 38951172, 2024). "We also note that 4-1BB is exclusively expressed among Foxp3+ CD4 Tregs in tumor-bearing mice, is absent among other T cell subsets, and is entirely absent in naïve mouse T cells." (PMID 38932362, 2024).